YAP1 (Yes1 associated transcriptional regulator)
Diseases named in the same sentence as YAP1 in open-access papers (continued):
Sharing a sentence is not in itself a finding about the gene and the disease.
cancer (continued). "Increases in YAP-1 activity are associated with cell proliferation and cancers, whereas phosphorylation of YAP-1 via MST1/2-LATS1/2 results in its cytoplasmic retention, and subsequent degradation, leading to loss of transcriptional activity and induction of apoptosis." (PMID 35846360, 2022). "Nuclear localization of YAP1 is known to activate multiple cancer-associated genes, and YAP1 activation with poor prognosis in various solid tumors is considered to be a result derived from all the complex effects of the cancer-associated gene that is put together." (PMID 36291755, 2022). "As expected, YAP1 was upregulated in AOM/DSS-induced colitis-associated cancer in C57BL/6J mice." (PMID 36479120, 2022). "Thus, our findings provided evidence of the carcinogenesis of YAP1 in human cancers and new insights into the mechanism underlying the function of YAP1 in mitochondrial dysfunction." (PMID 34257617, 2021). "Altogether, these results suggested that YAP1 could be a potential prognostic biomarker in some specific types of cancers and YAP1 over expression was significantly associated with poor prognosis in ACC, LGG, and PAAD." (PMID 34257617, 2021). "Similarly, this effect is linked to PAX3-FOXO1 co-localization with YAP1 in the nuclei of cancer cells." (PMID 34294128, 2021). "The involved fusion partners YES-associated protein 1 (Yap1) and mastermind-like domain containing 1 (Mamld1) are involved in several pathways, e.g., Hippo signaling pathway and Wnt/β-catenin pathway, active in various cancers." (PMID 34008056, 2021). "Thus, our findings provided evidence of the prognosis values of YAP1 in human cancers and new insights into the mechanism underlying the function of YAP1 in mitochondrial dysfunction." (PMID 34257617, 2021). "Therefore, once the SWI/SNF complex is inactivated by various mutations in cancer cells, YAP1 will be released and promote carcinogenesis." (PMID 34150758, 2021). "Taken together, these results indicated that YAP1 expression may serve as a potential diagnostic biomarker in these specific types of cancers." (PMID 34257617, 2021). "Additionally, the DriverDBv3 tool was also applied to determine the association between YAP1 expression and patients’ survival rates in pan-cancers." (PMID 34257617, 2021). "Thus, our findings provided evidence of the carcinogenesis of YAP1 in human cancers and new insights into the mechanisms underlying the role of YAP1 in mitochondrial dysregulation." (PMID 34257617, 2021). "However, YAP1 amplification and gain-of-function mutations are rarely detected in pan-cancer studies." (PMID 34771636, 2021). "Here, we explore some of the top ranked TRs including histone deacetylase 2 (HDAC2), estrogen receptor 1 (ESR1), TEA domain family member 4 (TEAD4), achaete-scute homolog 1 (ASCL1), androgen receptor (AR) and yes associated protein 1 (YAP1) in several cancer types." (PMID 33778495, 2021). "And LATS1/2 has been reported have a suppress role in cancer immunity, and this phenomenon may be a reason why YAP1 cytoplasmic localization is associate with the progression and poor prognosis of CRC." (PMID 33240680, 2020). "Thus, alteration of YAP1 expression and activity has also been shown to be associated with cancer development." (PMID 32827244, 2020). "YAP1 was known to be associated with therapy resistance of cancer treatment." (PMID 32293349, 2020). "In cancer, nuclear expression of YAP1 and its role in carcinogenesis may be linked to the inflammatory state induced by interleukin-6, which directly induces the activation of activating Src family kinase." (PMID 32218280, 2020).
cancer (continued). "That is why YAP1 rs11225163 polymorphism lost its association with cancer upon subclassification." (PMID 32283835, 2020). "In this study, the expression pattern of YAP1 in the Yunnan Cancer Hospital cohort reveal that the increased cytoplasmic YAP1 expression may be associated with the progression of CRC." (PMID 33240680, 2020). "YAP1 is overexpressed in a variety of cancers and is considered to be encoded by a proto‐oncogene." (PMID 30868052, 2019). "Overall, our study provides evidence that overexpression of YAP1 is significantly associated with the progression and recurrence of tumors and it might be a useful prognosticator in various cancers." (PMID 31613226, 2019). "Regarding YAP1, the protein encoded by YAP1 gene, it is negatively regulated by the Hippo signaling pathway, and its enhanced activity is believed to induce cell proliferation, migration and survival in several cancer types including cervical cancer." (PMID 30760827, 2019). "As typical for key regulators of proliferation, YAP1 has been linked to cancer progression." (PMID 31216773, 2019). "Association between YAP1 and cancer patients’ prognosis in GEPIA." (PMID 31613226, 2019). "A recent study revealed that the fluid SS (0.05 dyne/cm2), which may correspond to the velocity of fluid flow in the interstitium, can promote cancer motility through modulating the Yes-associated protein (YAP1)-related ROCK-LIMK-cofilin signaling pathway." (PMID 30651129, 2019). "Therefore, to clarify the mechanisms of YAP1 functioning in cancer, we explored the association between staining location of YAP1 and cancer patients’ prognosis." (PMID 31613226, 2019). "However, in several cancers, integrins have been linked to YAP1 expression as well as YAP1 activation by nuclear translocation of the protein." (PMID 30909436, 2019). "In that study we showed that YAP1 gene upregulation and worse clinical outcome of ccRCC patients as well as higher YAP1 protein expression in cancer tissue homogenates were associated with the clinical stage and pathomorphological features such as higher TNM and Fuhrman's stages." (PMID 29850494, 2018). "Surprisingly, loss of YAP1 expression led to dramatic alterations in phenotype and cancer behavior." (PMID 30504771, 2018). "Importantly, treatment with AZD0530 impaired cLIF cancer vascular dissemination and local invasion in vitro and in vivo, and its action was linked to increased phosphorylation of YAP1 (leading to trapping of YAP1 in the cytoplasm)." (PMID 30504771, 2018). "While the different roles of YAP1 in oncogenesis might be tissue- and cell context-specific, elevated YAP1 signaling in cancer cells has been linked to anti-cancer therapy resistance to agents such as taxol, doxorubicin, cisplatin and tamoxifen." (PMID 29228705, 2017). "YAP1 overexpression due to amplification of the YAP1 gene, loss of Hippo signaling by mutation, and/or down-regulation of core Hippo components have been found in many cancers." (PMID 27911857, 2017). "ECM rigidity and YAP1 activation can interact to maintain cancer-associated fibroblasts." (PMID 27036018, 2016). "On the contrary, the overexpression of hsa-miR-375 could contribute to inhibiting the expression of YAP1 that already had a copy number loss, may acting as a trigger for cancer." (PMID 26099552, 2015). "The rs1820453 located in the promoter region of YAP1 gene and the variant A>C change may cause down regulation of YAP1 which in turn might weaken the P73-dependent apoptosis of cancer cells and suppress the chemotherapy-induced cancer cell death." (PMID 24223879, 2013). "In addition to this regulation of YAP1 activity through the Hippo pathway, which is usually associated with cancer cells and/or hypoxia response, other kinases phosphorylate YAP1, regulating its localization, interaction with co-activators and transcriptional activity." (PMID 41198904, 2025).
cancer (continued). "Therefore, we stained adjacent sections for E-cadherin, vimentin, Slug, laminin 5, PRMT1, and PRMT5 and investigated whether the expression levels of these molecules and/or those of MST2 and YAP1 were associated with the cancer cell invasion pattern." (PMID 38444414, 2024). "Moreover, the expression of the YAP1 pathway gene signature was significantly and positively associated with the infiltrating levels of immunosuppressive stromal cells, including cancer-associated fibroblasts, macrophage and Tregs, but negatively associated with antitumoral CD4 Th1." (PMID 37173920, 2023). "Having established a regulatory role of YAP1 in p21 expression, we wondered to investigate whether the YAP1/p21 axis is implicated in chemotherapy, given that many first-line chemotherapeutic agents trigger cancer cells to undergo senescence." (PMID 33495462, 2021). "However, resistant cancer cells revive YAP1 activity by increasing mutations at these sites." (PMID 32722184, 2020). "Therefore, the dysfunction of Hippo/YAP1 pathway could imbalance the regulation, which could cause the cancer initiation." (PMID 31613226, 2019). "Moreover, Yap1 expression was also associated with cancer type and ER expression in mOS evaluation." (PMID 26695440, 2016). "Therefore, the low expression of hsa-miR-375 could possibly associates with deleted YAP1 expression balance, thus inducing the apoptosis of cancer cells." (PMID 26099552, 2015). "In contrast, YAP1 silencing markedly suppresses cell proliferation, induces cell cycle arrest via upregulation of p21 and p27, and impairs cancer cell migration." (PMID 41256331, 2025). "How mechanical signals influence the epigenetic landscape of YAP1, and conversely, how epigenetic modifications dictate the mechanical response of cancer cells, represents a fascinating and underexplored frontier in oncology." (PMID 40977060, 2025). "Considering the lack of effective strategies directly targeting deregulated YAP1 in human cancers, we next screened for small molecule compounds to mitigate YAP1 stability by determining the fluorescence intensity in A2780 cells stably expressing GFP-YAP1." (PMID 39827153, 2025). "Meanwhile, Co-upregulation of STK3 and YAP1 was also identified in both all cancer cell lines (R = 0.50) and STAD cell lines only (R = 0.38)." (PMID 40604818, 2025). "Cd274 expression in M2d cells and Pdcd1 expression in T cells were decreased when cancer Yap1 was silenced." (PMID 39946200, 2025). "Addressing these conflicts is not only essential for mechanistic understanding but also for developing context-aware therapeutic strategies targeting the YAP1–autophagy axis in cancer and infection." (PMID 40977060, 2025). "Given the significant challenges in directly inhibiting YAP1, targeting upstream regulators of YAP1 activity or stability present more promising strategies for treating cancers." (PMID 39968498, 2025). "In this study, we investigated the role of PP1γ in the progression of ESCC and its modulation of YAP1 and cancer stem cell markers such as SOX2." (PMID 40626009, 2025). "YAP1 exhibits indispensable functions in cell proliferation, tissue regeneration, mechanotransduction, tissue and organ homeostasis, as well as cancer metastasis." (PMID 40368918, 2025). "YAP1 signaling plays a pivotal role in promoting tumorsphere formation and enhancing cancer stem cell–like properties across various cancers." (PMID 40784457, 2025). "The differential expression of the TP63 and YAP1 genes in cervical SCC and ADC suggested that p63 and YAP1 play opposing roles in the progression of these two types of cancer." (PMID 40603978, 2025).
cancer (continued). "This pan-cancer perspective underscores YAP1 as a central node that integrates mechanical and epigenetic cues to orchestrate context-dependent oncogenic programs." (PMID 40977060, 2025). "Although the effect of YES1 on the YAP1/TAZ pathway has been reported in cancer studies, the understanding of its role in the cardiovascular processes remains unexplored." (PMID 40131761, 2025). "The oncogenic role of YAP1 extends across diverse cancer types, highlighting its universal significance in malignant progression." (PMID 40977060, 2025). "In cancer cells, sVASN promoted cell proliferation and migration by upregulating the YAP1/TAZ or mTOR-AKT pathways and it promotes stemness maintenance by regulating Notch1." (PMID 40430053, 2025). "Public GC scRNA-seq dataset was adopted, and the results illustrated that STK3 and YAP1 upregulation were largely enriched in the cancer cells within GC TME." (PMID 40604818, 2025). "Breaking this YAP1-LOX-mechanical feedback loop represents a promising therapeutic strategy for cancers." (PMID 40977060, 2025). "YAP1 acts as a transcriptional co-activator of the Hippo signaling that serves vital roles in cancer progression and drug resistance." (PMID 41184230, 2025). "Targeting the mechano-epigenetic axis of YAP1/TAZ offers promising therapeutic strategies for cancer treatment." (PMID 40977060, 2025). "Triple combination therapy with oHSV, RTx, and IGF1R blockade synergistically improved survival, abolished YAP1 expression, and reduced cancer cell self-renewal." (PMID 41510300, 2025). "Despite the importance of YAP1 in human cancers, the development of strategies to directly target YAP1 remains challenging." (PMID 39827153, 2025). "Introducing an active YAP1 mutant reversed these effects, further demonstrating the importance of KDELR1 in maintaining YAP1 activity and cancer aggressiveness." (PMID 41294677, 2025). "Studies have demonstrated that the high expression level and nuclear transition of YAP1 would induce the enhancement of multiple aggressiveness features of cancer cells, such as proliferation, migration and cancer stem cell population maintenance." (PMID 40604818, 2025). "The Hippo signalling pathway is important in regulating cell growth and its effector, YAP1, promotes cancer progression when active in the nucleus." (PMID 41294677, 2025). "Specifically, 37 cancer tissues with high YAP1 levels also exhibited relative high intensity of DUB3 staining, whereas 25% of samples with lower YAP1 levels displayed lower DUB3 staining." (PMID 39827153, 2025). "YAP1, a transcription factor that induces cancer stemness and is overexpressed in HNSCC, like SOX2, served as a control for efficient and high editing since it caused >50% editing in two different cell lines (UMSCC‐104, FADU)." (PMID 39736115, 2025). "In this study, we focus on the epigenetic regulation of four genes—ADIPOQ, GAS5, GATA4, and YAP1—selected for their established roles in fundamental cancer pathways and their potential for methylation-mediated dysregulation in TNBC." (PMID 41226688, 2025). "YAP1 has been found to be enriched in the LOX promotor region in a cancer cell line, suggesting a direct effect of YAP1 on LOX expression." (PMID 40753090, 2025). "Mainly induced by Helicobacter pylori (H. pylori) infection, the hyperactivation of Hippo-YAP1 signaling is commonly observed in GC patients and demonstrates close correlation with aggressive characteristics of cancer cells." (PMID 40604818, 2025). "YAP1 contributes to chemoresistance by modulating anti-apoptotic pathways, drug efflux mechanisms, and cancer stem cell maintenance." (PMID 40731926, 2025). "There is increasing evidence that YAP1 is becoming an appealing target for cancer treatment and contributing to our chemotherapy resistance insights." (PMID 40191726, 2025). "Cancer-associated fibroblasts (CAFs) secrete WNT2, which blocks DC differentiation, and maintain immunosuppressive stroma through YAP1 activation." (PMID 41050070, 2025).
cancer (continued). "As a comprehensive review, we aim to synthesize and critically evaluate the current understanding of YAP1 in cancer biology, with a specific focus on its dual role as a mediator of mechanical transduction and epigenetic regulation." (PMID 40977060, 2025). "Within this pathway, Yes-associated protein 1 (YAP1) serves as the core effector molecule and plays a critical role in the progression of various human cancers, including GC." (PMID 40535133, 2025). "As acknowledged, elevated transcriptional activity of YAP1 would significantly enhance the response to DNA repair of cancer cells, which would largely abolish the lethality of chemo drugs." (PMID 40604818, 2025). "YAP1 was reported to be highly upregulated in peritoneal carcinomatosis, conferring cancer stem cell properties and promoting metastasis." (PMID 39827153, 2025). "It has been reported that the RhoA/ROCK pathway upregulates YAP1 transcriptional activity, which mediates cancer invasion." (PMID 40388100, 2025). "YAP1, as a key effector of the Hippo signaling pathway, is frequently dysregulated in various cancers, including ESCC." (PMID 40626009, 2025). "Dysregulation of the Hippo pathway is implicated in many types of cancers with downregulated LATS1/2 signaling, resulting in increased accumulation of active YAP1 in the nucleus 33-36." (PMID 39781521, 2025). "In cancer cells, YAP1 is frequently overexpressed or hyperactivated and translocated into the nucleus, resulting in the transcriptional activation of target genes involved in cell proliferation, survival, and epithelial-mesenchymal transition (EMT)." (PMID 38967794, 2024). "As the core kinase of the Hippo signaling pathway, LATS2 regulates cancer progression by affecting YAP1 activity." (PMID 39247829, 2024). "AURKA-induced YAP1 phosphorylation was identified as a key trigger for cancer stem cell reprogramming." (PMID 38467828, 2024). "The uncontrolled activation of YAP1/TAZ has been linked to developing malignant features, such as cancer stem cell self-renewal, metastasis, and drug resistance." (PMID 38730733, 2024). "YAP1 and its paralog TAZ are normally repressed by the Hippo signaling pathway and Hippo pathway components are frequently mutated in human cancers." (PMID 38496413, 2024). "There is emerging link between proinflammatory cytokine signalling and YAP1 function in the context of inflammatory diseases and cancer." (PMID 37957015, 2024). "Expression of ALDH1A1, ALPL, ITGA6, CD44, PROM1 (CD133), LGR5, and YAP1 upregulated in the E2 and E3 phenotypes was consistent with cancer hallmarks including cell plasticity, self-renewal, and drug-tolerant persistence." (PMID 38915538, 2024). "Overexpression of the YAP1-S127A mutant readily reversed the suppressive effect on cancer cell migration induced by PRRG2 overexpression or ZBTB11 knockdown." (PMID 38355937, 2024). "Overall, this study provides a comprehensive insight into how YAP1 signaling drives cancer stemness and induces an immunosuppressive TME by influencing the infiltration of MDSCs and polarization of macrophages." (PMID 39630608, 2024). "In some carcinomas, cancer cell–intrinsic YAP1 modulates macrophage and myeloid-derived suppressor cell recruitment and differentiation, suggesting an immunomodulatory role." (PMID 38652549, 2024). "Beyond its involvement in tumorigenesis and cancer progression, YAP1 has been recognized as a significant contributor to therapeutic resistance in cancer." (PMID 38967794, 2024). "Next, we depleted cellular YAP1 in H1299-EV or H1299-PRRG2-Flag cells to measure potential changes in cancer cell metastatic behaviors." (PMID 38355937, 2024). "Taken together, these results suggest that the cancer-promoting behavior of DLAT in TNBC is contingent upon YAP1 activation." (PMID 39460738, 2024).